IFI44L (interferon induced protein 44 like)
Diseases named in the same sentence as IFI44L in open-access papers (continued):
Sharing a sentence is not in itself a finding about the gene and the disease.
ischemia (1 paper, 2021). A hypoperfusion of the BLOOD through an organ or tissue caused by a PATHOLOGIC CONSTRICTION or obstruction of its BLOOD VESSELS, or an absence of BLOOD CIRCULATION. "Increased expression of IFIT2, IFIT3 and IFI44L, as well as the ratios of IFIT2/IFIT3 and IFI44L/IFIT3, may boost apoptosis and aggravate ischemia-induced damage." (PMID 34884921, 2021).
ischemic cardiomyopathy (1 paper, 2021). Ischemic cardiomyopathy is a cardiomyopathy in which a weakness in the muscle of the heart due to inadequate oxygen delivery to the myocardium with coronary artery disease being the most common cause. "Three interferon stimulated genes (IFIT2, IFIT3 and IFI44L), as well as key pathways, have been identified as potential biomarkers and therapeutic targets for ischemic cardiomyopathy, and their alternations or mutations have been proven to be strongly linked to cardiac disorders." (PMID 34884921, 2021).
laryngeal carcinoma (1 paper, 2024). Carcinoma that arises from the laryngeal epithelium. "In human laryngeal carcinoma HEp2 cells, the expression of IFI44L is upregulated and can ultimately suppress the progression of laryngeal carcinoma by triggering apoptosis of laryngeal carcinoma cells through interaction with IFN-α." (PMID 39737399, 2024). "Moreover, IFI44L was also highly expressed in laryngeal carcinoma HEp2 cells." (PMID 39737399, 2024).
latent infection (1 paper, 2021). "We speculated that IFI44L plays an immunoregulatory role for HIV‐1 in host cells, one possible reason is that HIV‐1 can ensure latent infection by up‐regulating the expression of IFI44L." (PMID 33159419, 2021).
lung carcinoma (1 paper, 2021). "Here, we systemically analyzed the immune association of IFI44L with multiple tumor-infiltrating immune cells (TIICs) and immunomodulators through bioinformatics methods in The Cancer Genome Atlas (TCGA) lung cancer cohorts." (PMID 35047409, 2021). "Finally, tissue microarray analysis indicated that higher expression of IFI44L presented opposite relationship with pathological stage (p = 0.016) and a better outcome among lung cancer patients (p = 0.024)." (PMID 35047409, 2021).
lymph node tuberculosis (1 paper, 2018). Tuberculosis of the lymph node. "IFI44L is related to interferon-mediated inflammation in tuberculosis infection, such as lymph node tuberculosis and viral diseases." (PMID 29934568, 2018).
major depressive disorder (1 paper, 2024). An episode of depression lasting two or more weeks without an intervening episode of mania. "Many inflammation-related genes, including IFI44L, are downregulated in the brain tissue of patients with Major Depressive Disorder (MDD), underscoring the role of neuroinflammation in MDD." (PMID 39737399, 2024).
mixed connective tissue disease (1 paper, 2024). Mixed connective tissue disease (MCTD) is a rare autoimmune disorder that is characterized by features commonly seen in three different connective tissue disorders: systemic lupus erythematosus, scleroderma, and polymyositis. "However, very few studies have investigated the molecular mechanism of mixed connective tissue disease (MCTD) and the researchers found the epigenetic signal of IFI44L and confirmed that it is related to the heritability of MCTD." (PMID 39737399, 2024).
oral squamous cell carcinoma (1 paper, 2021). "Moreover, low IFI44L expression was identified as risk factors for oral squamous cell carcinoma patients’ OS." (PMID 34903206, 2021). "Moreover, by using univariate and multivariate Cox regression analysis based on GSE75540, we identified the low IFI44L expression as a risk factor for oral squamous cell carcinoma patients’ OS." (PMID 34903206, 2021). "Moreover, low IFI44L expression were identified as risk factors for oral squamous cell carcinoma patients’ OS." (PMID 34903206, 2021). "Moreover, high expression of IFI44L, one of the DEGs in the 6 reverse gene pairs, might be associated with favorable prognosis in oral squamous cell carcinoma patients and serve as a tumor suppressor by acting on the FRS-mediated FGFR signaling." (PMID 34903206, 2021). "Considering these previous findings, IFI44L might be a promising agent serving as a tumor suppressor in oral squamous cell carcinoma, possibly through acting on the FRS-mediated FGFR1, FGFR3, and downstream signaling pathways." (PMID 34903206, 2021). "Since low IFI44L expression showed to be associated with poor OS and DFS in oral squamous cell carcinoma patients, next, we performed GSEA functional annotation analysis on different characteristics in high- and low-IFI44L cases, attempting to identify signaling pathways related to IFI44L function." (PMID 34903206, 2021). "Notably, lower IFI44L expression was associated with poorer OS and DFS in oral squamous cell carcinoma patients, and IFI44L expression showed satisfactory predictive efficiency by ROC curve." (PMID 34903206, 2021). "However, the role of IFI44L in oral squamous cell carcinoma has never been investigated." (PMID 34903206, 2021).
psoriasis vulgaris (1 paper, 2022). Plaque psoriasis is the most common presentation of psoriasis. "In summary, we demonstrated that the presence of IL36G may mediate the keratinocyte expression of AVPs such as MX1, ISG15, IFI27, and IFI44L in psoriasis vulgaris." (PMID 36172384, 2022).
Rotavirus infection (1 paper, 2021). Infection with any of the rotaviruses. "Although little is known about the role of IFI44L in HuNoV infection, considering rotavirus being a gastrointestinal virus that induces similar clinical symptoms like HuNoV, we may use its effect on human rotavirus infection as a reference." (PMID 33494515, 2021).
trisomy 21 (1 paper, 2024). A chromosomal disorder consisting of the presence of an extra chromosome 21. "Ontologies such as response and defense against viruses, antimicrobial humoral immune responses mediated by antimicrobial peptides, and the regulation of myoblast fusion were associated with 20 genes in the Trisomy 21 with CHDs datasets (GSE196443 and GSE217557), including GNLY, IFI44L, and CXCL9." (PMID 39596121, 2024).
infection (45 papers, 2011 to 2025). The state of being infected such as from the introduction of a foreign agent such as serum, vaccine, antigenic substance or organism. "Because IFI44L was sufficient to distinguish AGS from hospitalized controls (often with concurrent infection), we hypothesize that the chronic inflammation associated with genetic interferonopathies may lead to a preferential upregulation of IFI44L." (PMID 38885315, 2024). "Of these genes, 6 (OASL, IFI27, IFIT1, IFIT3, RSAD2and IFI44L) were in protein-protein interaction network and at each stage of infection." (PMID 40255307, 2025). "Overexpression of IFI44 or IFI44L was shown to restrict RSV infection at an early time point after infection, whereas knockout of these genes in mammalian airway epithelial cells resulted in increased levels of RSV titer." (PMID 38896252, 2024). "As the duration of the infection, IFI44L expression was downregulated and the replication ability of the bacteria increased at 48 h." (PMID 34722780, 2021). "THP-1 cells were transfected with IFI44L specific shRNA (shRNA-IFI44L) and its scramble shRNA (Scr-shRNA) followed by M. tuberculosis H37Rv infection to examine the potential role of IFI44L in infected macrophages." (PMID 34722780, 2021). "In vivo, the expression of both Ifi44 and Ifi44l RNA was significantly upregulated rapidly after intranasal infection of BALB/c mice, detectable from 6 h (P < 0.05)." (PMID 32611756, 2020). "The classical ISGs were strongly induced by CDV-infection with particularly high levels for Isg15, Ifi44l, Isg56, Oas2 and Mx2 (fold change up to 928.35, 419.93, 179.05, 173.57 and 147.59)." (PMID 30939763, 2019). "One of the most interesting features of infection of Raji cells with XMLV was the up-regulation of the IFI44 and IFI44L genes that have been implicated as interferon-stimulated genes that confer resistance to HCV in vitro." (PMID 25912714, 2015). "Interestingly, IFI44L expression negatively modulates the proinflammatory state induced by IFN treatment or infection." (PMID 38885315, 2024). "Further, IFI44L expression was reduced during the acute infection phase compared to the recovery phase, indicating that the dynamic change of IFI44L could serve as a prognostic indicator for the therapeutic efficacy of the disease." (PMID 39737399, 2024). "The observed hypomethylation of IFI44L three months after infection in our study could reflect that it takes time to reverse the immune responses induced by infection." (PMID 35798818, 2022). "Addressing the antiviral response on a protein level revealed a different picture: while the antiviral protein MX144 was rapidly expressed by B cells upon infection, IFI44L, a negative regulator of the antiviral response, peaked on day 7 when transient infection already decreased again." (PMID 34169553, 2022). "Indeed, overexpression of IFI44 or IFI44L is sufficient to restrict RSV infection at an early time post-infection." (PMID 33968942, 2021). "In addition to HIV‐1, when rhesus monkeys are infected by the simian immunodeficiency virus, IFI44L is significantly upregulated up to 38‐fold on the 10th day of infection, and the up‐regulation of IFI44L is accompanied by up‐regulation of ISGs." (PMID 33159419, 2021). "Also, it was important to discuss thatthough our study identified a total of 9 genes that were common among three stages, but only 6 of them (OASL, IFI27, IFIT1, IFIT3, RSAD2and IFI44L) made into the PPI network whose expression level increases with the increase in the level of infection." (PMID 40255307, 2025). "Therefore, IFI44L upregulation decreased bacterial survival, promoted the polarization of macrophages and inflammatory cytokine secretion, and may help inhibit infection." (PMID 34722780, 2021). "We identified 6 genes found to be common in all three levels of infection whose expression level increases withthe increase in the level of infection (OASL, IFI27, IFIT1, IFIT3, RSAD2, IFI44L)." (PMID 40255307, 2025).
infection (continued). "The induction levels of antiviral genes—including DDX58, OAS1, OAS2, ISG15, MX2, IFI44L, RTP4, and IFNB1—were markedly reduced in KO cells compared to WT cells post-infection." (PMID 40872812, 2025). "According to the previous study, the identified 6 genes were found to be common in all three levels of infection whose expressionlevel increases with the increase in the level of infection (OASL, IFI27, IFIT1, IFIT3, RSAD2 and IFI44L)." (PMID 40322700, 2025). "While the number of significantly upregulated genes decreases to 37, these genes (e.g., ISG15, IFI6, IFI44L, HP, OAS1, IFI44, OASL, and IFI27) likely play a crucial role in the response to the progressing infection." (PMID 39282474, 2024). "During an in vitro infection system with hepatitis B virus (HBV), IFN-γ and IFN-α can remarkably regulate IFI44L expression." (PMID 39737399, 2024). "Shared genes upregulated with a higher log2 fold change in B/Victoria infection included known anti-viral proteins IFIT1-3, IFITM1, MX2, IFI44L and ISG15 along with mitochondrial-related gene CMPK2." (PMID 37766362, 2023). "Interferon (IFN)‐inducible 44 like (IFI44L) is an IFN‐stimulated gene, the expression of which is induced by IFN and human immunodeficiency virus (HIV)‐1 infection." (PMID 33159419, 2021). "The majority of the genes in this cluster were related to the immune response to infection including OAS-1/3, IFI44L, HLA-A and HLA-DRB-1/4." (PMID 34593881, 2021). "Knocking out these genes in human cells increases levels of infection, thus demonstrating a function for IFI44 and IFI44L in controlling RSV infection." (PMID 33968942, 2021). "With the insertion of K1L and C7L, this response was tempered; infection with NYVAC-C-KC-ΔB8RΔB19R induced increased transcriptional levels of seven of the genes shown, relative to NYVAC-C-KC (IFI35, IFI44, IFI44L, IFIT1, IFIT3, IFITM1, and IFITM2)." (PMID 22096477, 2011). "Integrated bioinformatic analysis predicted that interferon-induced protein 44-like (IFI44L) and interferon-α inducible protein-6 (IFI6) could also be used as potential biomarkers of infection." (PMID 37125151, 2023). "Components of interferon pathway and innate immunity (IFI44L, IFITM3, MX1, IRF7, OAS2, STAT2, etc.)are significantly upregulated in the acute phase of infection, while the expression levels of genes involved in translational elongation and protein biosynthesis are decreased." (PMID 26070066, 2015). "Expression levels of RSAD2, ISG15, IFI44L, and IFI27 were strongly correlated to serum sCD163 levels early after infection, but not to T-cell activation, suggesting that ISG expression may be linked to monocyte activation." (PMID 39104769, 2024).
tumor (21 papers, 2015 to 2025). "We found that elevated ERO1A, OSBPL3 and IFI44L protein expression in tumor tissues was significantly associated with late T stage which represent depth of tumor invasion and late TNM stage." (PMID 28881752, 2017). "Of note, overexpression of TGFBI and interferon-induced proteins IFIT2, IFIH1 and IFI44L in the residual tumor were also associated with reduced RFS." (PMID 26021444, 2015). "Elevated ERO1A, OSBPL3 and IFI44L protein expression in tumor tissues may cause patients’ median survival time 18.83%-44.07% (ERO1A:44.07%, OSBPL3: 18.83%and IFI44L, 42.37%) shorter than patients who without." (PMID 28881752, 2017). "In the application of clinical diagnosis, IFI44L can be used as a potential target for tumor drug development, as well as a differential target for bacterial and viral diagnosis." (PMID 39737399, 2024). "Low IFI44L expression was also correlated with increased tumour size, disease relapse, advanced disease stage and poor clinical survival in HCC patients." (PMID 39233332, 2024). "When IFI44L is overexpressed, patients’ survival rates are higher, thusthis gene has the potential to function as an immune-related suppressor in tumor therapy." (PMID 39737399, 2024). "In the clinic, the expression level of interferon‐induced protein 44‐like (IFI44L) is significantly reduced in HCC tumour tissues." (PMID 39233332, 2024). "Unfortunately, many investigators have only discovered that IFI44L influences the growth, migration, and apoptosis of tumor cells." (PMID 39737399, 2024). "ROC curve analysis showed that CXCL8, DDX60, IFI44l, RSAD2, and RTP44 had better diagnostic efficiency for normal and tumor tissues, and the combined diagnosis was more effective." (PMID 34384424, 2021). "In the ulcerated tumor, B cells showed increased markers associated with type-2 responses such as CCL17, IL4R, and decreases in interferon-stimulated genes (IFI44L, STAT1, IFITM1, MX1, IRF1)." (PMID 34583709, 2021). "In a tumour disease, IFI44L activated the met/Src signaling pathway and had effects on cancer stemness, metastasis, and drug resistance." (PMID 34722780, 2021). "We investigate the relationship between IFI44L and various tumor-infiltrating immune cells (TIICs) in TCGA-LUAD samples and TCGA-LUSC samples, respectively." (PMID 35047409, 2021). "IFI44L, a type I interferon-stimulated gene, has been shown to be involved in human carcinogenesis and tumor progression." (PMID 31803541, 2019). "Clinical relevance of low expression of IFI44L with larger tumor size, disease relapse, advanced stages, and poor outcomes in HCC patients was also first identified." (PMID 29848298, 2018). "Western blotting analysis also revealed that all of ten pairs of matched HCC tumor tissues expressed lower level of IFI44L in comparison with the matched normal tissues." (PMID 29848298, 2018). "We also first identified that the expression of IFI44L decreased in tumor tissues and correlated with several poor clinical outcomes in HCC patients." (PMID 29848298, 2018). "Downregulation of IFI44L expression found in HCC tumor tissues is compatible with the tumor suppressor role in HCC we discovered above." (PMID 29848298, 2018). "Taken together, we first demonstrated that IFI44L is a novel tumor suppressor to affect cancer stemness, metastasis, and drug resistance via regulating Met/Src signaling pathway in HCC and can be serve as an important prognostic marker." (PMID 29848298, 2018). "Our study has demonstrated that IFI44L as a novel tumor suppressor in HCC through perturbation of Met/Src signaling." (PMID 29848298, 2018). "Low expression of IFI44L levels also correlated with larger tumor size, disease relapse, advanced stages, and poor clinical survival in HCC patients." (PMID 29848298, 2018). "Thus, this review provides a detailed overview of IFI44L, covering its biological functions and mechanisms, as well as its correlation with tumor and non-tumor diseases." (PMID 39737399, 2024).
tumor (continued). "It inhibits tumor growth, prevents viral and bacterial replication, and reduces inflammation progression via its involvement in signal transduction, and genetic, and DNA methylation level of IFI44L." (PMID 39737399, 2024). "IFI44L - Interferon Induced Protein 44 Like (IFI44L) is a tumor suppressor." (PMID 38304289, 2023). "Consistent with previous studies, the expression of IFI44L is positively correlated with the prognosis of patients with OC, and the high expression of IFI44L may play an anti-tumor role in OC." (PMID 34384424, 2021). "IFI44L might be a novel tumor suppressor that affects cancer stemness, metastasis, and drug resistance in cancer cells." (PMID 32226026, 2020). "Although the function of IFI44L is unclear, some studies have revealed that it is involved in the inflammatory response, and may be a tumor suppressor." (PMID 33134167, 2020). "Taken together, these findings reinforced that the functional role of IFI44L as a tumor suppressor and it could implicate in Met/Src signaling pathway in HCC." (PMID 29848298, 2018). "Moreover, higher percentage of HCC patients with low expression level of IFI44L had larger tumor size then patients with high expression level of IFI44L (64% vs 36%, P = 0.002)." (PMID 29848298, 2018). "Clinically, the expression level of IFI44L significantly reduced in HCC tumor tissues." (PMID 29848298, 2018). "Thus, our data suggested that IFI44L may play as a tumor suppressor role in restoring chemosensitivity and affecting cancer stemness." (PMID 29848298, 2018). "Furthermore, we evaluate the tumor suppressor role of IFI44L in regulating cancer metastasis." (PMID 29848298, 2018). "Interferon-induced protein 44-like (IFI44L), a type I interferon-stimulated gene (ISG), has been reported to be involved in innate immune processes and to act as a tumor suppressor in several cancers." (PMID 35047409, 2021). "The Human Protein Atlas database showed that the protein expressions of DDX60, IFI44L, RSAD2, and RTP44 in tumor tissues were higher than those in normal tissues." (PMID 34384424, 2021). "Previous studies also reported that IFI44L, TRIM22, OAS1, OAS2, and MX2 inhibited tumor proliferation and metastasis, indicating that the transcriptional regulation of STAT1/2 could limit the development of OS." (PMID 40956299, 2025). "The network indicated that hsa-miR-6799-5p and hsa-miR-6759-5p, two tumor suppressor-related miRNAs, could interact with EIF2AK2 and IFI44L simultaneously." (PMID 35495164, 2022). "Among these parameters, age, gender, tumor differentiation, HBV surface antigen, anti-HCV antibody, and the tumor number were not significantly different in patients with low versus high expression levels of IFI44L." (PMID 29848298, 2018). "Furthermore, the ROC curve analysis showed that hub gene (CXCL8, DDX60, IFI44L, RSAD2, and RTP4) could distinguish OC from normal tissues, and the diagnosis effect of tumor tissue was better, and the combined diagnosis of five genes was the best." (PMID 34384424, 2021). "However, the immunological role of IFI44L in tumor has not been discovered yet, especially in NSCLC." (PMID 35047409, 2021).